ADGRL3 (adhesion G protein-coupled receptor L3)
Description:
Orphan adhesion G protein-coupled receptor (aGPCR), which mediates synapse specificity. Ligand binding causes a conformation change that triggers signaling via guanine nucleotide-binding proteins (G proteins) and modulates the activity of downstream effectors. ADGRL3 is coupled with different classes of G alpha proteins, such as G(12)/G(13), G(s), G(i) or G(q), depending on the context. Coupling to G(12)/G(13) G proteins, which mediates the activation Rho small GTPases is the most efficient. Following G protein-coupled receptor activation, associates with cell adhesion molecules that are expressed at the surface of adjacent cells to direct synapse specificity. Specifically mediates the establishment of Schaffer-collateral synapses formed by CA3-region axons on CA1-region pyramidal neurons in the hippocampus (By similarity). Localizes to postsynaptic spines in excitatory synapses in the S.oriens and S.radiatum and interacts with presynaptic cell adhesion molecules FLRT3 and TENM2, promoting synapse formation (By similarity). Plays a role in the development of glutamatergic synapses in the cortex (By similarity). Important in determining the connectivity rates between the principal neurons in the cortex (By similarity). [Isoform 1]: Orphan adhesion G protein-coupled receptor (aGPCR), which mediates synapse specificity. Ligand binding causes a conformation change that triggers signaling via guanine nucleotide-binding proteins (G proteins) and modulates the activity of downstream effectors, such as adenylate cyclase. Isoform 1 is specifically coupled to G(s) G proteins and mediates activation of adenylate cyclase activity. Following G protein-coupled receptor activation, undergoes liquid-liquid phase transition, associates with (1) cell adhesion molecules that are expressed at the surface of adjacent cells, as well as (2) PDZ-containing proteins, such as SHANK3 and DLG4, in the cytoplasm to direct synapse formation.
Synonyms: KIAA0768; LEC3; LPHN3; CIRL3; CL3
Tractability: Antibody: UniProt places it where antibodies can reach, with high confidence; its Gene Ontology location is reachable by antibodies, with high confidence; UniProt predicts a signal peptide or a membrane-spanning region. PROTAC: ubiquitination databases record sites on it; its protein half-life has been measured.
Safety:
Unwanted effects reported when the protein is acted on. In parentheses: how it was acted on, where the effect was seen, and who reports it.
nicotine dependence (source: ClinPGx)
Gene: Protein-coding gene on chromosome 4 (61,200,326 to 62,078,335, forward strand). Ensembl gene ENSG00000150471.
Subcellular location: Cell membrane; Postsynaptic cell membrane; Cell projection, axon; Cell junction
Gene Ontology:
Molecular function: calcium ion binding; G protein-coupled receptor activity; protein binding; cell adhesion mediator activity; carbohydrate binding; transmembrane signaling receptor activity
Biological process: cell-cell adhesion; Rho-activating G protein-coupled receptor signaling pathway; excitatory synapse assembly; G protein-coupled receptor signaling pathway; neuron migration; synapse assembly; cell surface receptor signaling pathway
Cellular component: plasma membrane; anchoring junction; axon; cell-cell junction; glutamatergic synapse; membrane; postsynaptic membrane
Genetic constraint (gnomAD): Loss-of-function variants: 36 observed, 105.39 expected, observed/expected ratio (o/e) 0.34, 90% interval 0.26 to 0.45. The upper end of that interval is the gene's LOEUF score, 0.45, which puts it in group 2 of 6, group 1 being the genes least tolerant of losing a copy. Missense variants: 1,295 observed, 1,564.5 expected, observed/expected ratio (o/e) 0.83, 90% interval 0.79 to 0.87. Synonymous variants: 573 observed, 583.59 expected, observed/expected ratio (o/e) 0.98, 90% interval 0.92 to 1.05.
Homologues: Orthologues: chimpanzee ADGRL3 (99% identical), pig ADGRL3 (97% identical), mouse Adgrl3 (97% identical), rat Adgrl3 (96% identical), macaque ADGRL3 (95% identical), guinea pig ADGRL3 (85% identical), rabbit ADGRL3 (82% identical), tropical clawed frog adgrl3 (76% identical), zebrafish adgrl3.1 (70% identical), zebrafish adgrl3.2 (68% identical). Paralogues in human: ADGRL2 (56% identical), ADGRL1 (51% identical), ADGRL4 (17% identical), ADGRE5 (15% identical), ADGRE2 (15% identical), ADGRB1 (14% identical), ADGRE1 (14% identical), ADGRE3 (13% identical), ADGRD1 (13% identical), ADGRG6 (13% identical), ADGRG4 (12% identical), ADGRB2 (12% identical), and 30 more.
Diseases named in the same sentence as ADGRL3 in open-access papers:
ADGRL3 is named in the same sentence as 64 diseases in open-access papers, as found by Europe PMC text mining. Sharing a sentence is not in itself a finding about the gene and the disease. The quoted sentences say what the papers report.
attention deficit-hyperactivity disorder (16 papers, 2014 to 2025). A disorder characterized by a marked pattern of inattention and/or hyperactivity-impulsivity that is inconsistent with developmental level and clearly interferes with functioning in at least two settings (e.g. at home and at school). "Single-nucleotide polymorphisms in ADGRL3 that result in haploinsufficiency have been associated with an increased risk of attention-deficit/hyperactivity disorder (ADHD) and are predictive of susceptibility to substance use disorders." (PMID 40766670, 2025). "The Latrophilin 3 (LPHN3) gene (recently renamed Adhesion G protein‐coupled receptor L3 (ADGRL3)) has been linked to susceptibility to attention deficit/hyperactivity disorder (ADHD) and vulnerability to addiction." (PMID 27247960, 2016). "ADGRL3 was associated with attention-deficit/hyperactivity disorder." (PMID 32993537, 2020). "Previous studies have shown that the gene encoding the adhesion G protein-coupled receptor L3 (ADGRL3; formerly latrophilin 3, LPHN3) is associated with Attention-Deficit/Hyperactivity Disorder (ADHD)." (PMID 33504901, 2021).
colorectal cancer (3 papers, 2021 to 2025). A primary or metastatic malignant neoplasm that affects the colon or rectum. "Based on the Human Protein Atlas, Adhesion G protein-coupled receptor L3 (ADGRL3) is frequently present in breast, prostate and colorectal cancers." (PMID 34830327, 2021).
epilepsy (2 papers, 2019 to 2023). A brain disorder characterized by episodes of abnormally increased neuronal discharge resulting in transient episodes of sensory or motor neurological dysfunction, or psychic dysfunction. "Combined with their potential role in glucose metabolism and insulin resistance, such evidence suggests that MYO10 and ADGRL3 could be related to the underlying mechanisms of the comorbidity of PCOS in epilepsy." (PMID 40217327, 2023). "This group of patients also have high-frequency mutations of MYO10 and ADGRL3, which may facilitate precise early screening of PCOS in female patients with epilepsy." (PMID 40217327, 2023).
Oppositional defiant disorder (2 papers, 2016 to 2022). An enduring pattern of uncooperative, defiant, and hostile behavior towards authority figures that does not involve major antisocial violations, is not accounted for by the child's developmental stage, and results in significant functional impairment. "ADGRL3 variants predispose to ADHD, modulate brain metabolism, and predict ADHD severity, ADHD comorbidity with conduct disorder (CD), oppositional defiant disorder (ODD), substance use disorder (SUD), and response to stimulant treatment." (PMID 36151371, 2022).
amyloidosis (1 paper, 2024). A disorder characterized by the localized or diffuse accumulation of amyloid protein in various anatomic sites. "Additional astrocyte hub genes in the ETC, including NRXN1, CADM1, MACF1, MAGI2, LRP4, GJA1 and ADGRL3, have been identified as markers of a reactive astrocyte state, implicating them in amyloidosis, regulation of neuroinflammation, cellular interactions." (PMID 38913039, 2024).
heart failure (1 paper, 2022). Inability of the heart to pump blood at an adequate rate to meet tissue metabolic requirements. "Further understanding of the instructive cues and parental cardiomyocyte populations that give rise to ADGRL3 and NPPA/NPPB-expressing cardiomyocytes may provide new insights and opportunities to intervene in the pathogenesis of human heart failure." (PMID 35959412, 2022).
substance abuse (1 paper, 2023). The use of a drug for a reason other than which it was intended or in a manner or in quantities other than directed. "Despite being strongly associated with ADHD and several other impulse-control disorders (e.g., substance abuse) the underlying mechanisms by which ADGRL3 affects externalizing behavioral phenotypes are not well characterized." (PMID 37783687, 2023).
tumor (16 papers, 2010 to 2025). "The gene for adhesion G protein-coupled receptor latrophilin-3 (aGPCR Lphn3 or ADGRL3) is targeted by tumor-specific somatic mutations predominantly affecting the conserved GAIN domain where most aGPCRs are cleaved." (PMID 35741042, 2022). "Additionally, fifteen genes were associated with cancer control; among these, three were related to immunity (MAGT1, RFXANK and SKAP2), two (ADGRL3 and TENM3) were related to cell adhesion, and two (ADAM11 and TEP1) were found to be tumor suppressor genes." (PMID 34107880, 2021).
ADGRL3 also shares sentences with these, for which no sentence is quoted: cancer (14 papers); infection (7); breast carcinoma (5); Hypertension (4); breast tumors (3); colon cancer (3); glioma (3); neurodevelopmental disorder (3); autism spectrum disorder (2); bladder cancer (2); lung carcinoma (2); Neurological disease (2); viral infection (2); acute monocytic leukemia (1); acute myeloid leukemia (1); alcohol dependence (1); Alzheimer disease (1); Anxiety (1); asthma (1); Atrophy (1); autism (1); autoimmune disease (1); Autoimmunity (1); bladder tumors (1); brain ischemia (1); chronic kidney disease (1); clear cell carcinoma (1); conduct disorder (1); congenital heart defects (1); COVID-19 (1).
A further 26 diseases each share a sentence with ADGRL3 in 1 paper.